IGF1R (insulin like growth factor 1 receptor)
Diseases named in the same sentence as IGF1R in open-access papers (continued):
Sharing a sentence is not in itself a finding about the gene and the disease.
breast cancer (continued). "Compared to North American cohorts, the present study population had a relatively low BMI that may influence the relationship between IGF1R signaling and breast cancer prognosis." (PMID 28030849, 2017). "Study for breast cancer patients treated by anti-IGF-1R agents was unexpected." (PMID 28427155, 2017). "Furthermore, it has been shown that low concentrations of adiponectin rapidly increase IGF-1R phosphorylation in ERα+ breast cancer cells, and that the use of ERα siRNA prevents this effect." (PMID 29036907, 2017). "Breast cancer with secondary resistance often shows induced IGF1R signaling, which may also explain metformin resistance." (PMID 29137418, 2017). "The IGF1 receptor (IGF1R), which mediates the biological actions of both ligands, exhibits potent antiapoptotic and cell-survival activities and is regarded as a major player in breast cancer development." (PMID 28706506, 2017). "Thus, IGF-1R inhibitors have yet to show satisfactory clinical benefit to patients with more prevalently diagnosed cancers, including breast cancer and non-small cell lung cancer, in the overall patient population." (PMID 28046018, 2017). "Indeed, trastuzumab resistance is a common problem in ErbB2+ breast cancers because tumor cells can circumvent ErbB2 inhibition by activating IGF1R." (PMID 28947975, 2017). "The observation that high IGF1R and SphK1 expression are prognostic for improved overall survival is paradoxical, given that the literature suggests IGF1R and SphK1 are oncogenic mediators in breast cancer." (PMID 29207959, 2017). "It is well accepted that IGF1R can regulate ER, and SphK1 is regulated by estrogen, in breast cancer, hence the therapeutic implication that co-targeting them may be clinically effective in ER-positive breast cancer." (PMID 29207959, 2017). "Furthermore, IGF1R was shown to be differentially expressed with variable prognostic impact among breast cancer subtypes." (PMID 28706506, 2017). "Phenformin also blocked epithelial-mesenchymal transition, decreased the invasive phenotype, and suppressed receptor tyrosine kinase signaling, including insulin receptor substrate 1 and IGF1R, in ErbB2-overexpressing breast cancer cells and mouse mammary tumor-derived tissues." (PMID 28947975, 2017). "In addition to breast cancer cells, the impact of nuclear IGF1R was also assessed in two prostate cell lines, P69 and M12." (PMID 28945762, 2017). "In addition to PI3K, IRS-1/2 has become another potential target against the IGF-1R network in breast cancer." (PMID 29152592, 2017). "Moreover, there is still conflicting prognostic vs. preclinical data in relation to the benefits of IGF1R targeted therapies in breast cancer which highlights the need for a better understanding of IGF1R signaling." (PMID 29207959, 2017). "Indeed, it has been reported that phosphorylated IGF-1R/1R is detected in all breast cancer subtypes (luminal, 48.1%; TNBC, 41.9%; HER2, 64.3%), with higher mortality." (PMID 28046018, 2017). "We report the use of multiplexed super-resolution imaging (Exchange-PAINT) followed by mean-shift clustering and random forest analysis to measure the precise distributions of five receptor tyrosine kinases (RTKs) from the ErbB, IGF-1R and Met families in breast cancer cells." (PMID 28939861, 2017). "However, the role of IGF1R in breast cancer, as well as the complicated interplay between other factors in treatment resistance, is far from understood." (PMID 28489591, 2017). "IGFs and the IGF1R are possibly involved in the cellular response to Herceptin, as they may activate the Akt/Bad and mTOR signaling pathways in breast carcinoma cells." (PMID 28507201, 2017). "IGF-1R TKIs also potentiated the effects of cisplatin in a panel of breast cancer cell lines." (PMID 27472395, 2016). "A different breast cancer study revealed IGF-1R gene as another target for 515-5p." (PMID 27092493, 2016).
breast cancer (continued). "Taken together these findings suggest that CD24 cell surface expression may serve as a valuable biomarker in order to identify mammary tumors that will positively respond to targeted IGF1R therapies." (PMID 27179633, 2016). "Here, we take advantage of the same cell models to determine if the trastuzumab-resistant breast cancer cells become refractory to lapatinib, and to explore whether erbB3- and IGF-1R-initiated signaling pathways differentially modulate lapatinib sensitivity." (PMID 26621843, 2016). "Moreover, a dynamic interplay between IGF and ERα in breast cancer cells has been demonstrated, where IGF-1R increase ERα phosphorylation and activity via mTOR/S6K1 and ERα mediates IGF-1R, IRS-1 and IGF ligand expression." (PMID 27765027, 2016). "Overall, these results indicate that IGF-1R inhibition may be effective in combination with cisplatin in breast cancer cells that exhibit different levels of sensitivity to either the TKI or cisplatin." (PMID 27472395, 2016). "Additionally, gene set enrichment analysis of the spatio-temporal gene set with a gene set of 24 mouse models for breast cancer led us to identify a potential new function for insulin-like growth factor 1 (Igf1r) in the basal epithelium during lactogenesis." (PMID 27808166, 2016). "In addition, interactions with HER2 have been suggested, as cross-talk between IGF1R and HER2 has been implicated in resistance against trastuzumab, a monoclonal antibody used in breast cancer treatment to target HER2 receptors." (PMID 27376028, 2016). "Importantly, for the first time, synergistic inhibition is demonstrated when combining IGF-1R and mTOR targeting agents in breast cancer cells." (PMID 27765027, 2016). "A previous study has also demonstrated miR-630 could improve patient response to HER-targeting drugs by targeting IGF-1R in HER2-overexpressing breast cancer." (PMID 26595523, 2016). "Furthermore, limited activity of Igf1r accelerates tumorigenesis and promotes more aggressive phenotypes in prostate and breast cancer in mice." (PMID 27861515, 2016). "IGF1R promotes cancer cell survival and proliferation and prevents apoptosis, and, additionally it was shown that IGF1R levels are significantly elevated in most common human malignancies including breast cancer." (PMID 27179633, 2016). "Moreover, we demonstrate that IGF1R-KD abolished both CD24+ cells capacity to form mammary tumors and lung metastatic lesions." (PMID 27179633, 2016). "Moreover hybrid receptors - constituted of IR and IGF1R heterodimers – have been shown to have cellular biological effects resembling those of the IGF1R and were found in colon cancer, thyroid cancer and breast cancer cell lines and tissues." (PMID 27405474, 2016). "Taken all together, our results here indicate that cell surface expression of CD24 in breast tumor cells may serve as a valuable biomarker to identify breast cancer patients that will benefit from anti-IGF1R therapy." (PMID 27179633, 2016). "Similarly, IGF1R gene amplification has been reported only in a small number of breast cancer and melanoma cases, suggesting that this genetic event is not a common mechanism in malignancy." (PMID 27446805, 2016). "The same may not be true for IGF signaling: it is known that PIK3CA-mutated breast cancer cells remain responsive to IGF stimulation and are growth delayed by IGF-1R inhibition." (PMID 27200287, 2016). "Thus, combined IGF-1R/mTOR inhibition plus hormone therapy in breast cancer cells presents as a viable therapeutic option." (PMID 27765027, 2016). "Since the early 1980s, when interest in IGF1R’s role in breast cancer development began, preclinical studies demonstrated that IGF1R is involved in cell transformation in addition to mediating tumor-promoting functions such as proliferation, antiapoptosis and cancer cell dissemination." (PMID 27179633, 2016). "In breast cancer, IGF1R expression correlates most strongly with luminal breast cancers." (PMID 25964777, 2015).
breast cancer (continued). "In this study, we aimed to determine the effect of PARP inhibition on estrogen-induced growth of breast cancer cells and examine whether the potential effect is linked to PDZK1 and IGF-1R expression." (PMID 26183824, 2015). "Neoadjuvant breast cancer therapy can induce changes in IGF-1R expression." (PMID 25680198, 2015). "Furthermore, the Yee lab has shown that while IGF1R is reduced in tamoxifen resistant breast cancer cells, InsR is still expressed and able to signal via insulin to promote growth." (PMID 25964777, 2015). "Numerous in vitro studies demonstrate IGF1R as a driver of self renewal, stem cell surface markers, migration, and invasion in both normal and cancerous tissues and tumor initiation in hepatic, lung, prostate, and breast cancers." (PMID 25964777, 2015). "When luminal and triple-negative subtypes were assessed separately, IGF1R overexpression (score 3+) was comparable in frequency to that reported in human breast cancer in which more than 45 % of the triple-negative breast carcinomas show strong expression of IGF1R." (PMID 26449867, 2015). "IGF1R overexpression is common and related to a poor outcome in canine invasive mammary carcinoma, particularly in the triple negative subtype, as in human breast cancer." (PMID 26449867, 2015). "Indeed, there are emerging reports suggesting that synergy can be achieved with the combination of CDK4/6 inhibitors and PI3K inhibitors in breast cancer or with insulin-like growth factor receptor 1 (IGF1R) inhibitors in pancreatic cancer." (PMID 26337082, 2015). "Prior studies from the Yee laboratory demonstrated that down-regulation of IGF-1R signaling in a variety of breast cancer cell lines increases insulin sensitivity by increasing cell surface expression of holo-IR due to a reduction in hybrid IR/IGF-1R cell surface expression." (PMID 26106366, 2015). "Indeed, a preclinical study showed that co-inhibition of HER-1 and IGF-IR sensitized HER-1/IGF-1R expressing human breast cancer cells to radiation." (PMID 26350593, 2015). "IGF1R-specific IgG antibodies were significantly elevated in early stage breast cancer patients." (PMID 26173023, 2015). "Most importantly, our data demonstrate that changes in membranous IGF-1R expression may be a prognostic factor in neoadjuvantly treated breast cancer patients." (PMID 25680198, 2015). "IGF-1R expression can change during breast cancer treatment." (PMID 25680198, 2015). "Indeed, studies in transgenic mice reveal that epithelial-specific overexpression of IGF-1R induces mammary tumors with basal-like characteristics whereas epithelial-specific down-regulation of IGF-1R produces tumor with a more claudin-low molecular profile." (PMID 25743390, 2015). "In addition to these screens, the breast cancer susceptibility genes, BRCA1 and BRCA2, have recently been shown to regular IGF-1R expression or influence the downstream signaling." (PMID 26217584, 2015). "Activation of IGF-1R plays a crucial role in breast cancer progression and metastasis." (PMID 26536657, 2015). "In summary, IGF-1R has a prognostic value in breast cancer, its expression can change during treatment, and it may play a role in resistance to conventional breast cancer therapies." (PMID 25680198, 2015). "Indeed, extensive crosstalk between ER and IGF1R is now well-established from several in vitro studies, which demonstrate a synergistic effect of IGF1R and ER on the proliferation of human breast cancer cells." (PMID 26449867, 2015). "The significantly increased IGF-1R expression level was reported in breast cancer tissues." (PMID 26536657, 2015). "Transcriptional suppression of the IGF-1R gene by BRCA1 has also been reported in breast and endometrial cancer, and loss-of-function mutation of BRCA1 leads to amplification and constitutive activation of the IGF-1R pathway in breast cancer." (PMID 26510816, 2015).
breast cancer (continued). "We examined the expression profiles of the IGF1, IGF1R, IGFBP2 (IGF-binding proteins), and IGFBP3 proteins in breast tumor tissue and their relationships with all-cause and breast cancer-specific survival up to 17 years postdiagnosis in a multiethnic series of 358 patients in Hawaii, USA." (PMID 25619494, 2015). "Furthermore, using genetic ablation of IGF1R expression in a basal-like breast cancer xenograft model, it has been shown that IGF1R is involved in breast tumorigenesis." (PMID 25749031, 2015). "For example, tumor tissue microarrays show that 87% of primary breast tumors express IGF1R; however, the active phosphorylated form of IGF1R/InsR, as measured by immunohistochemistry (IHC), is only present in roughly 50% of breast cancers where it correlates with poor survival." (PMID 25964777, 2015). "We have shown a strong relationship between PDZK1 and IGF-1R expression in human breast cancer and that PDZK1 may be a determinant in breast tumorigenesis." (PMID 26183824, 2015). "Considering the luminal and triple negative immunophenotypes separately, the IGF1R 0–1+, 2+ and 3+ scores occurred in 17 (36.2 %), 14 (29.8 %) and 16 (34.0 %) luminal canine mammary carcinomas and in 17 (16.5 %), 40 (38.8 %) and 46 (44.7 %) triple-negative canine mammary carcinomas respectively." (PMID 26449867, 2015). "The aim of the present study was to investigate if the insulin-like growth factor-1 receptor (IGF1R) signaling pathway was activated or deregulated in breast cancer patients and to explore if any of the markers were prognostic, with or without adjuvant tamoxifen." (PMID 25362932, 2014). "Estrogens increase IGF binding and IGF1R mRNA levels in breast cancer cells, suggesting that a potential mechanism by which estrogens stimulate breast tissue proliferation involves sensitization to the mitogenic effects of IGFs by enhancing IGF1R concentrations." (PMID 24904527, 2014). "Furthermore, stimulation of insulin-like growth factor-1 receptor (IGF-1R) in human breast cancer results in the activation of BRK." (PMID 24523872, 2014). "Similarly, CDK6 demonstrated r>0.7 in only 4 cancers (glioblastoma, head and neck cancer, lung adenocarcinoma, and lung squamous cancer) while IGF1R had r>0.7 in only one cancer (breast cancer)." (PMID 24874471, 2014). "Furthermore, leptin transactivated and induced the expression of ER, EGFR, HER2 and IGF-1R in breast cancer." (PMID 24716804, 2014). "In vitro and in vivo studies in rhabdomyosarcoma and breast cancer reported IGF1R mRNA and protein expression could be used to identify tumors with increased sensitivity to anti-IGF1R therapy." (PMID 25170759, 2014). "However, data regarding it's prognostic role in early breast cancer remain controversial, with some studies reporting an adverse impact of IGF1R overexpression on clinical outcomes and others suggesting a favorable prognostic role." (PMID 24637962, 2014). "miR-122 was downregulated in breast cancer and overexpression of miR-122 could inhibit cell proliferation and tumorigenesis of breast cancer by targeting IGF1R." (PMID 24788655, 2014). "IGF1 and IGF1R have been reported to play roles in the early transformation of mammary cells, induction of mammary epithelial hyperplasia in a transgenic mouse model, and breast cancer cell growth cells." (PMID 24392142, 2014). "The IGF-1R is frequently overexpressed in human myeloma, head and neck cancer and breast cancer, suggesting that aberrant IGF-1R expression may contribute to initiation and progression of malignancies." (PMID 24810113, 2014). "miR-375, which was downregulated and predicted to target IGF1R in trastuzumab-resistant HER2-positive breast cancer cells, could indeed inhibit the cellular luciferase activity in a reporter construct containing the 3′-UTR of IGF1R." (PMID 24571711, 2014). "Studies of the prognostic role of IGF1R in breast cancer have so far given discrepant results." (PMID 25362932, 2014).
breast cancer (continued). "Similarly, we also use LMAb1 to treat MCF-7 cells, an IGF-1R-positive breast cancer cell line, which showed satisfactory anti-tumor activity by flow cytometry, cell proliferation and transwell in vitro (data not show)." (PMID 25424625, 2014). "Similar to the effects of miR-375 overexpression, silencing of IGF1R partially restored the sensitivity of SKBr-3 cells to trastuzumab (p < 0.01), suggesting that IGF1R, as a target gene of miR-375, is critically involved in trastuzumab resistance of breast cancers." (PMID 24571711, 2014). "Recently, Lorenzatti and colleagues found that CCN6, a tumor inhibitory protein, could suppress the expression of EMT transcriptional factor ZEB1 in breast cancer cells through attenuation of IGF-1R signaling." (PMID 23663564, 2013). "In this study, we demonstrated that IGF-1R could serve as a novel marker for a particular stem/progenitor population within breast cancer and its signaling pathway is critical for the survival and maintenance of BCSCs." (PMID 23663564, 2013). "Coupling of PNA with IGF-1R targeting probe can increase its uptake of the breast cancer cells." (PMID 23533377, 2013). "BRCA1 may also be a potential regulator of the insulin-like growth factor 1 receptor in human breast cancer cell line HCC1937." (PMID 24321281, 2013). "IGF1-R expression was found in almost 40% of male breast cancers, suggesting that IGF1-R might be the driving growth factor receptor in male breast cancer." (PMID 23308200, 2013). "We next determined whether knockdown of IGF-1R suppresses the tumorigenicity of IGF-1R expressing breast cancer stem/progenitors." (PMID 23663564, 2013). "Type 1 insulin-like growth factor receptor (IGF-1R) is a transmembrane tyrosine kinase receptor which plays a critical role in signaling cell survival and proliferation and has become a new target for breast cancer treatment." (PMID 23533377, 2013). "Given the importance of IGF-1R signaling in the progression of breast cancer, we next examined whether IGF-1R could serve as a marker for BCSCs." (PMID 23663564, 2013). "In breast cancer, activation of the IGF-1R could result in stimulation of proliferation and metastasis through activation of insulin receptor substrate-1 and insulin receptor substrate-2." (PMID 23663564, 2013). "Chromosome 15q26, where IGF-1R is located was found to be amplified in basal-like breast cancer." (PMID 22415797, 2012). "Therefore the panel EGFR, MET, HER2, GLUT1, CAIX, and IGF1-R detected 84.2% of the basal/TN ductal breast cancers compared to 45.0% of the luminal-type, and 18.3% of the lobular breast cancer cases." (PMID 22695343, 2012). "Moreover, our data extended previous studies indicating that monoclonal antibodies targeting both IGF1R and HRs markedly inhibit the growth of thyroid and breast cancer cells with high HR:IGF1R ratios." (PMID 22438913, 2012). "Finally, significant crosstalk between IGF-1R and the androgen receptor in prostate cancers or estrogen receptor in breast cancers has been observed, though this combination remains to be validated clinically." (PMID 24212944, 2011). "Finally, mammary tumors were also induced in transgenic mice overexpressing Igf1R in mammary epithelium." (PMID 21646685, 2011). "Hyperinsulinemia could stimulate IGF-1R and hybrid receptors although the clinical significance of this in breast cancer development is still unclear." (PMID 21773024, 2011). "An increase in the relative abundance of IR-A might significantly increase formation of IGF1R and IR-A hybrid receptors, IR-A/IR-B heterodimers, and IR-A homodimers in breast cancer tissues." (PMID 22046260, 2011). "Additional reports have characterized a relationship between IGF-1R and EGFR signaling in aggressive, drug-resistant breast cancer cells and have speculated that IGF-1R signaling plays a role in the development of gefitinib resistant EGFR tumors." (PMID 21854628, 2011).